RAPH1 (Ras association (RalGDS/AF-6) and pleckstrin homology domains 1)
Description:
Mediator of localized membrane signals. Implicated in the regulation of lamellipodial dynamics. Negatively regulates cell adhesion.
Synonyms: PREL-2; ALS2CR18; ALS2CR9; KIAA1681; LPD; PREL2; RMO1; RalGDS/AF-6
Tractability: Antibody: UniProt places it where antibodies can reach, with high confidence; its Gene Ontology location is reachable by antibodies, with high confidence. PROTAC: ubiquitination databases record sites on it; its protein half-life has been measured.
Gene: Protein-coding gene on chromosome 2 (203,394,345 to 203,535,451, reverse strand). Ensembl gene ENSG00000173166.
Subcellular location: Cell membrane; Cell projection, lamellipodium; Cell projection, filopodium; Cytoplasm, cytoskeleton
Subcellular location (Human Protein Atlas): Nuclear bodies; Plasma membrane; Cytosol
Gene Ontology:
Molecular function: protein binding; protein-macromolecule adaptor activity
Biological process: intracellular signal transduction; signal transduction
Cellular component: plasma membrane; cytosol; cell leading edge; cytoskeleton; filopodium; lamellipodium
Genetic constraint (gnomAD): Loss-of-function variants: 16 observed, 64.3 expected, observed/expected ratio (o/e) 0.25, 90% interval 0.17 to 0.38. The upper end of that interval is the gene's LOEUF score, 0.38, which puts it in group 1 of 6, group 1 being the genes least tolerant of losing a copy. Missense variants: 1,215 observed, 1,282.9 expected, observed/expected ratio (o/e) 0.95, 90% interval 0.9 to 0.99. Synonymous variants: 491 observed, 474.76 expected, observed/expected ratio (o/e) 1.03, 90% interval 0.96 to 1.11.
Homologues: Orthologues: chimpanzee RAPH1 (99% identical), macaque RAPH1 (99% identical), mouse Raph1 (92% identical), rat Raph1 (91% identical), tropical clawed frog raph1 (77% identical), guinea pig RAPH1 (73% identical), zebrafish raph1b (62% identical), zebrafish raph1a (60% identical), dog RAPH1 (56% identical), Drosophila melanogaster pico (23% identical), Caenorhabditis elegans mig-10 (19% identical). Paralogues in human: APBB1IP (26% identical), GRB10 (14% identical), GRB14 (12% identical), GRB7 (11% identical).
Diseases named in the same sentence as RAPH1 in open-access papers:
RAPH1 is named in the same sentence as 16 diseases in open-access papers, as found by Europe PMC text mining. Sharing a sentence is not in itself a finding about the gene and the disease. The quoted sentences say what the papers report.
breast carcinoma (6 papers, 2022 to 2025). "It has been shown that RAPH1 promotes aggressiveness and radioresistance in breast cancer and that high expression of RAPH1 protein is associated with breast cancer shorter survival." (PMID 40666499, 2025). "In breast cancer cells, RAPH1 has the capacity to promote three-dimensional (3D) cancer cell invasion through interaction with actin-elongating Ena/VASP proteins and the Scar/WAVE complex." (PMID 38062011, 2023). "Similar findings were observed in estrogen receptor-positive breast cancer cell lines that had co-expression of RAPH1-i3 and FOXQ1." (PMID 38062011, 2023). "A previous study has reported that RAPH1 mRNA upregulation is correlated with poor prognosis in breast cancer." (PMID 38062011, 2023). "Taken together, these findings support the pivotal role for the nuclear isoform of RAPH1 in mediating breast cancer aggressive phenotype." (PMID 38062011, 2023). "High RAPH1 expression has been correlated with aggressive breast cancer phenotypes and provides independent prognostic value in invasive breast cancer." (PMID 36687508, 2022). "Next, we sought to determine the mechanism by which RAPH1-i3 and FOXQ1 regulate the aggressiveness of breast cancer cells." (PMID 38062011, 2023). "RAPH1, SOX14, DPEP1, and UBL4A have a significant role in the invasion or metastasis of breast cancer, cervical cancer, colon cancer, and pancreatic ductal adenocarcinoma, respectively." (PMID 37378426, 2023). "Similarly, Nuclear isoform of RAPH1 (named RAPH1-i3) interacts with FOXQ1 and can promote breast cancer progression and radio-resistance." (PMID 41347087, 2025). "Targeting RAPH1-i3 and FOXQ1 may provide a therapeutic strategy for improving radioresistance in breast cancer." (PMID 38062011, 2023).
major depression (2 papers, 2021 to 2022). "However, findings for the postpartum samples showed only a trend of association between the expressions of CAT, CD59, and RAPH1 blood markers and depression scores." (PMID 33479202, 2021).
autoimmune disease (1 paper, 2022). A disorder resulting from loss of function or tissue destruction of an organ or multiple organs, arising from humoral or cellular immune responses of the individual to their own tissue constituents. "Irrespective of this, two candidate causal SNPs and genes including rs3087243 (RAPH1) and rs61839660 (IL2RA, RBM17, PFKFB3, LINC02649) were found to be common between T1D and other autoimmune diseases." (PMID 35773720, 2022).
diarrheal disease (1 paper, 2022). The condition of having at least three loose or liquid bowel movements each day. "Our study reports five such proteins, RAPH1, GCNT7, ADAMTS1, GLI1, and SEC31B, which are strong binding partners of other significant proteins and could thus be targeted for the discovery of a common medication system against diarrheal disease." (PMID 36473896, 2022).
E. coli infections (1 paper, 2022). "The first identified protein is RAPH1, a common protein that downregulates from S. Typhimurium and E. coli infections." (PMID 36473896, 2022).
glial tumors (1 paper, 2023). "RAPH1 can also cooperate with oncogenic Ras to drive the development of glial tumors." (PMID 38062011, 2023).
lung carcinoma (1 paper, 2021). "The deletion of the chromosomal region 2q containing the Lpd gene (RAPH1—Ras-associated and pleckstrin homology domain-containing protein 1) is commonly observed in head and neck squamous cell cancer, neuroblastoma and lung carcinoma." (PMID 34771501, 2021).
cancer (4 papers, 2022 to 2025). A tumor composed of atypical neoplastic, often pleomorphic cells that invade other tissues. "Further investigation revealed that the effect of RAPH1-v3 in cancer cells is mediated at least in part by increasing the activity of the transcription factor STAT3, which is an established oncogene in TNBC." (PMID 39777582, 2025). "We then found that the most significant DEGs were tightly associated with progression of cancers, including PTMA, HNRNPR, RAPH1, TRAF3IP1, CNBP, and PRR15." (PMID 41347062, 2025).
tumor (3 papers, 2023 to 2025). "Additionally, RAPH1-i3 upregulation was associated with advanced tumor stage and reduced disease-free survival in TNBC patients." (PMID 38062011, 2023). "Moreover, high expression of nuclear RAPH1 is significantly associated with advanced tumor stage and reduced DFS in TNBC patients." (PMID 38062011, 2023). "Overexpression of RAPH1-i3 in tumor tissues is associated with poor prognosis in TNBC patients." (PMID 38062011, 2023). "Higher RAPH1-i3 expression was significantly correlated with advanced tumor stage of TNBC patients (P = 0.0015)." (PMID 38062011, 2023). "While VASP and RAPH1 expression did not significantly differ between non-tumor and tumor tissue, CRK and CRKL exhibited an opposite expression pattern." (PMID 39126118, 2024).
RAPH1 also shares sentences with these, for which no sentence is quoted: asthma (1 paper); cervical cancer (1); colitis (1); colon cancer (1); depression (1); invasive breast carcinoma (1); pancreatic ductal adenocarcinoma (1).